EGFR (epidermal growth factor receptor)
Diseases named in the same sentence as EGFR in open-access papers (continued):
Sharing a sentence is not in itself a finding about the gene and the disease.
glioma (continued). "Notably, EGFR alterations (mutations and amplifications, considered together in this study) and PTEN alterations (mutations and deep deletions) affected almost exclusively IDH-WT gliomas." (PMID 37372972, 2023). "Furthermore, EGFR was proven to influence the glutamine metabolism in glioma cells." (PMID 37446288, 2023). "In this paper, we investigated whether Cer metabolism is altered in the U87MG human glioma cell line overexpressing EGFRvIII (EGFR+ cells) to elucidate their possible interplay in the mechanisms regulating GBM survival properties and the response to the alkylating agent temozolomide (TMZ)." (PMID 37895074, 2023). "Activated EGFR signalling drives the occurrence and progression of the majority of GBM tumours, and the secreted E‐cadherin protein variant encoded by E‐cadherin‐RNA plays an important role in activating EGFR signal transduction in GBM and promoting tumorigenicity of glioma stem cells." (PMID 36457281, 2023). "Thus, EGFR signaling plays a crucial role in intracellular communication between glioma cells." (PMID 37241023, 2023). "Finally, we examined whether CD31, EGFR, and VEGFA expression were associated with glioma’s prognosis in the TCGA dataset." (PMID 37534312, 2023). "Based on the promising results obtained and on the fact that EGFR/PI3K signaling is common to both glioma and TNBC, we hypothesized that such small molecules might also be able to modulate key tumorigenic events in BC cells, particularly in those with brain tropism." (PMID 37568789, 2023). "To examine whether inhibition of CD47 can sensitize the inhibitory effect of EGFR inhibitors on tumor growth, we treated the mice bearing the brain tumor derived from CT‐2A glioma cells with EGFR inhibitor afatinib or an anti‐CD47 antibody alone or with a combination of both reagents." (PMID 37541303, 2023). "However, it has yet to be determined whether ANO1 also binds with NOTCH receptors in a similar manner to EGFR in glioma." (PMID 36497413, 2022). "EGFR inhibitor Lapatinib and Gefitinib had higher IC50 in the low-risk group than that in the high-risk group, suggesting EGFR inhibitors could be potential pharmacological therapies for patients with high-risk glioma." (PMID 36698888, 2022). "The prognosis of glioma patients is divergent, which may be related to different tumor grades, mutation of isocitrate dehydrogenase (IDH), amplification of epidermal growth factor receptor (EGFR) and other factors." (PMID 36110851, 2022). "Thus, GALNT2 knockout decreases the level of phosphorylated EGFR, which could improve the malignant characteristics of glioma." (PMID 37786890, 2022). "However, EGFR upregulation, oxygen deficits, vascularization, and post-surgical damage can effectively enhance the infusion of VV into glioma and increase its tumor selectivity, suggesting that intravenous administration of VV is possible and effective in this disease." (PMID 35795092, 2022). "MRI-coupled fluorescence molecular tomography (MRI-FMT) determines epidermal growth factor receptor status in brain cancer while advanced MRI techniques contribute to biological and imaging features of glioma and immune system interactions and in the clinical management of adult gliomas." (PMID 35163262, 2022). "Thus, EGFR inhibitors are recommended adjuvant treatments in pediatric glioma." (PMID 36046036, 2022). "Epidermal growth factor receptor (EGFR) was shown to interact with SLC7A11 protein to maintain its localization at the cell membrane; increased cystine uptake and enhanced glutamate export associated with tumor growth and invasiveness has been observed in EGFR-expressing glioma cells." (PMID 35280777, 2022). "However, the association between the risk of gliomas and EGFR SNPs has not been studied in Korean populations." (PMID 36347915, 2022).
glioma (continued). "Moreover, in KEGG pathways, top-ranked eight PDGFA-involved categories according to P-Value were EGFR tyrosine kinase inhibitor resistance, Ras signaling pathway, Pathways in cancer, Glioma, MicroRNAs in cancer, Rap1 signaling pathway, focal adhesion, and PI3K-AKT signaling pathway." (PMID 35105853, 2022). "Secondly, the molecular detection information was not complete and did not include 1p/19q co-deletion, ATRX mutation, EGFR amplification, etc., but this molecular information was of great significance to the diagnosis and treatment of glioma, so it needs to be improved in future research." (PMID 36614997, 2022). "Also, the prognostic effects of SPATS2L in glioma and the associations between SPATS2L and EGFR and CDKN2A alterations are unknown." (PMID 33959491, 2021). "Upregulated expression of CRNDE induces EGFR (epidermal growth factor receptor) activation, resulting in apoptosis inhibition through an increased Bcl2 (B-cell CLL/lymphoma 2)/Bax (BCL2-associated X) ratio and an association with poor survival in glioma patients." (PMID 34316694, 2021). "However, the connections between CDKN2A and EGFR in glioma are unclear." (PMID 33959491, 2021). "Therefore we further validated RRAD overexpression in EGFR high human glioma specimens." (PMID 33980886, 2021). "Moreover, binary interactions in cis, e.g. with glioma-associated proteins, such as the EGF receptor (EGFR), may also be affected by increased fluctuation." (PMID 33929593, 2021). "In addition, the intracellular localization of LanCL2, not EGFR, was associated with the grade of gliomas." (PMID 34461927, 2021). "However, using BRAFV600E inhibitors alone could easily induce glioma cells’ resistance to them, the escape mechanisms of glioma cells included the up‐regulation of the Wnt pathway and increased activity of receptor tyrosine kinases, including EGFR." (PMID 34482648, 2021). "Additionally, somatic mutations in KMT2C (FDR = 0.046) and CDH1 (FDR = 0.045) were found to be significantly associated with later-onset BRCA, while those in EGFR (FDR = 1.34E-7) and IDH1 (FDR = 1.34E-7) were found to be significantly associated with later-onset gliomas." (PMID 34788626, 2021). "Despite its relative prevalence in high-grade gliomas such as GMB, EGFRvIII, a constitutively activating mutation with intragenic deletion of exons 2 to 7, is not often found in LGG; however, some oncogenic mutations of EGFR, such as A289V, R108K, and G598V, are found in LGG patients." (PMID 34552618, 2021). "Therefore, patients with IDH1-mut glioma aged 48–63 years old might benefit from EGFR inhibitor therapy." (PMID 32819307, 2020). "However, the apoptosis rates of normal glial cells induced by gefitinib alone or combination treatment were dramatically less than those in the glioma cells, which may be resulted from the lower expression of EGFR in normal cells than glioma cells." (PMID 32820249, 2020). "MiR-450a-5p could also increase drug sensitivity of another EGFR inhibitor osimertinib in glioma." (PMID 32820249, 2020). "In addition, approximately 60% of all gliomas have an amplified gene coding epidermal growth factor receptor (EGFR), which, by binding to epidermal growth factor (EGF), contributes to its increased activity and promotes proliferation and intracellular signaling disorders." (PMID 32977537, 2020).
glioma (continued). "Importantly, the knockdown of GOLPH3 expression in the human glioma cell lines A172, U87, U118, and U251 promotes the endocytosis and downregulation of EGFR, emphasizing the putative role that GOLPH3 might have in regulating the function of this receptor." (PMID 33238647, 2020). "Most of the driver genes of glioma showed decreased expression when mutated but not for EGFR." (PMID 32328184, 2020). "Although these mutations occurred in the context of mutant EGFR (implying genetic cooperation), this does not preclude these being drivers in other contexts without EGFR, as exemplified by Pten and Nf1 also causing multiple glioma types with other drivers." (PMID 32727536, 2020). "Also, the relationship between the detecting frequency, variants and biological mechanisms of NTRK fusions with typical molecular pathology in adult glioma, such as IDH mutation, EGFR amplification, MGMT promoter methylation and so on, are remain unknown." (PMID 33330081, 2020). "Thus, we investigated the EGFR expression and pathway activity in glioma cells." (PMID 31068339, 2019). "Similarly, the EGFR signaling also is activated by hypoxia in gastric cancer and glioma." (PMID 30487162, 2019). "To test whether 6PGD is phosphorylated upon EGFR activation, we generated U87 or U251 glioma cells stably expressing EGFR (U87/EGFR or U251/EGFR), and infected these cells and human primary GSC11 GBM cells with the lentivirus expressing Flag-tagged 6PGD (Flag-6PGD)." (PMID 30824700, 2019). "Moreover, the macrophage-related gene signature was found to be predictive of the targeted therapy outcome in glioma patients and outperformed existing gene signatures including conventional EGFR signature and an immune-related gene signature, which were verified using the validation dataset." (PMID 31097021, 2019). "The EGFR-induced NF-κB activation may be attributable to BTK pathways—however this is not currently clear given the molecular mechanism of EGFR induced activation of NF-κB in glioma is currently unclear." (PMID 29561760, 2018). "Thus, EGFR is undoubtedly a preferred key gene and target site in terms of treatment of glioma." (PMID 29652919, 2018). "Therefore, we also analysed glioma VAMCs, constituting the cellular source of EMT transcription factors in our cohort, for the most frequent and specific glioma-associated genetic aberrations namely IDH1 mutation, 1p/19q LOH as well as EGFR amplification." (PMID 29844871, 2018). "Furthermore, a recent study claims an EGFR‐dependent effect of EGFL7 on glioma growth." (PMID 30065025, 2018). "Furthermore, HB-EGF is expressed with EGFR in approximately 40% of human glioma tissues." (PMID 29864158, 2018). "The mimic of miR-7 microRNA was studied as a human glioma growth inhibitor in vitro and in vivo; miR-7 regulates the expression of several target proteins simultaneously, including the tumor growth and apoptosis regulators EGFR, PI3K, and AKT-2, in human glioma U251 cells." (PMID 30096839, 2018). "Thus, NQO1 inhibitors might provide innovative pharmacological treatment strategy for therapeutic intervention to the most malignant EGFR amplified gliomas." (PMID 30595797, 2018). "In addition, FoxM1 activated EGFR/AKT/GSK3β signaling pathway in glioma cells." (PMID 29700308, 2018). "However, the molecular mechanism of EGFR-induced activation of NF-κB in glioma is still unclear." (PMID 28946903, 2017). "Similar to the findings from univariate analysis, CNG of EGFR (OR =9.61, 95% CI =2.83-32.7, P <0.001), HER3 (OR =4.47, 95% CI =1.35-14.75, P =0.01) and HER4 (OR =5.07, 95% CI =1.50-17.06, P =0.009) was still significantly associated with cancer-related death in glioma patients." (PMID 29190914, 2017).
glioma (continued). "In this study, we investigated how AQP5 gene silencing might influence the proliferation and apoptosis of human glioma cells and the involvement of the EGFR/extracellular signal-regulated kinase (ERK)/MAPK pathway to provide a new direction for the treatment of glioma." (PMID 28404978, 2017). "We observed constitutive cholesterol synthesis in multiple glioma tumor sphere lines harboring a variety of alterations in this pathway, including both EGFR and PDGFRA amplification and PTEN deletion, suggesting that cholesterol synthesis inhibition might be useful across a wide genomic spectrum." (PMID 28118603, 2017). "Alternatively, downregulation of EGFRvIII activation at both tyrosine phosphorylation and expression levels by the combination treatment may be important to suppress the signaling from EGFR that contributes to growth and survival benefits for glioma cells in vivo." (PMID 26778701, 2016). "Therefore, Kindlin-2/YB-1/β-catenin/EGFR signaling is critical for glioma development." (PMID 27713156, 2016). "The genetic variants in EGFR that have been associated with glioma risk are not closely linked in the genome, and therefore these genotypes could give disparate result." (PMID 26839018, 2016). "Therefore, we hypothesized that Kindlin-2 could regulated EGFR transcription in glioma cells through its interaction with β-catenin and YB-1." (PMID 27713156, 2016). "We hypothesized that SNPs in EGFR could impact the prognosis of glioma patient." (PMID 27437777, 2016). "A study cohort of 57 glioma cases, examining tumoral heterogeneity via immunohistochemistry found that in one case the over-expression and amplification were localized to one half of the glioma, with the other half demonstrating normal levels of EGFR expression." (PMID 25688333, 2015). "Importantly, cisplatin, as well as other DNA-targeting anti-cancer drugs including camptothecin and doxorubicin, was shown to induce EGFR tyrosine phosphorylation, and its blockage with the EGFR TKI AG1478 enhanced cisplatin-induced cell death in human glioma cells." (PMID 26568478, 2015). "Therefore, EGFR is an important target for the clinical treatment of glioma." (PMID 25950430, 2015). "The data further suggested that not all IDH1/2 wild-type lower grade gliomas are uniformly aggressive and additional markers including TERTp mutation and EGFR amplification should be examined in the clinical management of lower-grade gliomas with wild-type IDH1/2." (PMID 26369702, 2015). "The contribution of CD151 and associated LB integrins to glioma aggressiveness may not be completely dependent on their crosstalk with the EGFR pathway." (PMID 26377974, 2015). "Targeting non-coding RNA could sensitize human glioma cell to anti-EGFR therapy." (PMID 25823657, 2015). "Finally, EGFR-induced signaling in glioma cells stimulates expression of TF, FVII, and PAR-2, thereby increasing TF/VIIa-mediated PAR-2 activation in cancer cells, and cancer cells may secrete aFVII that can act alone to activate PAR-2." (PMID 26573921, 2015). "In addition to the shut-down of EGFR signalling, other combinatorial treatments could be envisaged based on the rational knowledge of glioma cells molecular alterations." (PMID 25576921, 2015). "In the earlier part of the study, we showed that combined treatment is effective in Asian glioma cells expressing wild-type EGFR; herein, we sought to determine whether the combination of Nimotuzumab and rapamycin may also be effective in mutant EGFRvIII-expressing human glioma cells." (PMID 25886314, 2015). "Additionally, nearly all classical gliomas harbored EGFR amplifications." (PMID 24755548, 2014).
glioma (continued). "In addition, PKM2 is upregulated in EGFR-induced pathways in glioma malignancies." (PMID 23840737, 2013). "Interestingly, PTPRK-wt expression reduced EGFR and β-catenin protein levels in glioma." (PMID 23696788, 2013). "Thus, re-expression of PTPRK and consequent intercellular homophilic interactions in glioma cells might induce contact inhibition of growth and thereby send downstream signals to reduce EGFR and β-catenin levels." (PMID 23696788, 2013). "It is thought provoking that mutant EGFR is not sufficient to cause glioma in animal models." (PMID 23508692, 2013). "However, the role of EGFR overexpression in the prognosis of gliomas remains controversial." (PMID 23946790, 2013). "Furthermore, epidermal growth factor receptor and methylguanine-DNA methyltransferase (MGMT) promotor hypermethylation were reported to be associated with histological transformation and recurrence of gliomas." (PMID 24088576, 2013). "This study involved longitudinal analysis samples of primary and recurrent gliomas to determine whether the progression of low- and high-grade gliomas is associated with the promoter methylation of the DNMT1, MGMT and EGFR genes by PCR-based restriction enzyme assay." (PMID 22264301, 2012). "In addition, it is possible that haplotypes and locus–locus interactions within the EGFR gene may be correlated with the development of glioma." (PMID 22662167, 2012). "Subsequent testing of the same drug combination in a different syngeneic glioma model that lacked EGFR amplification but was more susceptible to sunitinib in vitro demonstrated no survival benefit when treated with gefitinib or sunitinib or the gefitinib and sunitinib combination." (PMID 23056179, 2012). "Previous studies focused only on one or two variants in the EGFR gene, which might not sufficiently capture the effect of susceptibility loci in Chinese glioma patients." (PMID 22662167, 2012). "Genetic analyses demonstrated that EGFR and PI3K initiate malignant neoplastic transformation via a combinatorial genetic network composed primarily of other pathways commonly mutated or activated in human glioma, including the Tor, Myc, G1 Cyclins-Cdks, and Rb-E2F pathways." (PMID 19214224, 2009). "While the presence of FIG‐ROS in glioma has been seen in only two tumor‐derived cell lines to date, overexpression of the native ROS kinase does occur somewhat more frequently in actual tumors (∼30% of cases) and activates similar signaling cascades to those directed by EGFR and PDGFR." (PMID 19076778, 2009). "Moreover, gliomas with EGFR amplification clustered close to tumor stem cells." (PMID 18492260, 2008). "Versican has been found to be co-localised with hyaluronan, CD44 and tenascin in the pericellular matrix in tumours, and because of its ability to interact these modulators of invasion and EGFR, versican may contribute to the malignant properties of glioma cells." (PMID 17453002, 2007). "Furthermore, these mutations in the EGFR tyrosine kinase domain have not been found in patients with glioma." (PMID 17353924, 2007). "EGFR amplification and EGFRvIII have been shown to increase glioma proliferation and invasion in vitro; therefore logically EGFR and/or EGFRvIII expression could exhibit a proclivity towards the development of multifocal disease, gliomatosis cerebri or ependymal seeding." (PMID 16236164, 2005). "In addition, EGFR amplification was present in 4/11 successfully grafted oligodendrogliomas in our series, indicating that the tumorigenic role of this alteration affects various subtypes of gliomas." (PMID 14676814, 2003).